AR (androgen receptor)
Diseases named in the same sentence as AR in open-access papers (continued):
Sharing a sentence is not in itself a finding about the gene and the disease.
tumor (continued). "Furthermore, a small peptide specifically designed to block AR and Src interaction increased apoptosis in LNCaP tumor xenografts." (PMID 28671964, 2017). "IHC analysis also proved that the activated AR signaling pathway contributes to tumor growth." (PMID 28423563, 2017). "The loss of Rb contributes to tumor progression and androgen receptor activity in CaP yet in inhibition of miR-30e* did not affect total Rb levels." (PMID 28978058, 2017). "In addition, the funnel plots via Begg’s test showed no significant bias across publications regarding differences in AR/ERβ expression in normal vs. tumor samples, patient genders, tumor grades/stages, or RFS/PFS rates." (PMID 28362839, 2017). "Significant heterogeneity existed in the meta-analysis of the association of AR expression with non-tumor/tumor (I2 = 95.7%; P < 0.001) or tumor stage (I2 = 82.1%; P < 0.001), but not with gender (P = 0.653) or tumor grade (P = 0.113)." (PMID 28362839, 2017). "In addition to the tumor suppressive miRNAs, oncogenic role of miRNAs to activate AR signaling has been documented." (PMID 28783103, 2017). "Consequently, inhibiting FKBP52‐regulated AR activity through MJC13 drug treatment in L(−)ID4 xenografts significantly attenuated the tumor growth in vivo." (PMID 28252832, 2017). "In resistant tumor tissues, glucocorticoid receptor could increase the expression of AR target genes thus contributing to cancer progression, consistent with overlapping transcriptomes and cistromes for both receptors." (PMID 29214142, 2017). "High AR levels appear to sensitize a number of PC preclinical models to the inhibitory effect of SPT, raising the possibility that tumor AR expression might be useful in predicting response to SPT." (PMID 29210989, 2017). "Inhibition of both non-genomic and genomic pathways of AR may be necessary to eradicate tumor dependency of AR." (PMID 28144231, 2017). "Statistical results showed that gelsolin expression in PCa was associated with disease status, tumor grade, cigarette smoking, serum PSA level, lymphovascular infiltration and the expression of androgen receptor, AKR1C2 and epidermal growth factor receptor (EGFR)." (PMID 29100377, 2017). "Tumor AR expression was assessable in 671 of 718 cases (93%) where tumor tissue was available." (PMID 28643022, 2017). "Studies in castration resistant cancers, in which there is AR overproduction, result in hypersensitivity to small amounts of circulating androgens, indicating that the overproduction of the receptor contributes to the development and tumor progression." (PMID 28499383, 2017). "Interestingly, the cells located around the blood vessels in the high-grade tumor tissues expressed AR at an extraordinarily high level." (PMID 28423563, 2017). "The androgen receptor is the central regulator of nominal and tumor prostate biology." (PMID 28275218, 2017). "Interestingly, according to analyses of ER-negative tumors using the METABRIC dataset, 18 (4.1%) cases with AR-low/FOXA1-high tumor showed the worst survival and 114 (26.0%) with AR-high/FOXA1-high presented worse DFS with statistical significance." (PMID 29137314, 2017). "Indeed, androgen-mediated overexpression of miR-27a results in the reduction of prohibitin, a well-known tumor-suppressor gene and co-repressor of the AR, with a subsequently increased expression of AR genes and increased PCa cell growth." (PMID 28275218, 2017). "We know that AR signalling in stroma is less sensitive than in epithelial cells, and thus more vulnerable to systemic changes in androgen levels, or on altered supply based on local tumour microarchitecture and/or vascular supply." (PMID 28117763, 2017). "The in vitro results were confirmed in an in vivo xenografts, providing evidence of a greater inhibitory activity of pulsed supraphysiological T supplementation than continuous treatment, both in terms of tumor volume and decreased AR, p-ARser81, PSA and CDK1 staining." (PMID 29371946, 2017).
tumor (continued). "Archived tumor tissues for AR IHC staining were available for 7 patients." (PMID 28957377, 2017). "Moreover, brain dissemination is probably the result of progressive dedifferentiation of primary tumor, shown by reduction of ER and AR expression in metastases." (PMID 28467804, 2017). "Patients with AR-positive NMI tumor were also found to have a significantly lower risk for tumor recurrence, compared to those with AR-negative NMI, but not for disease progression." (PMID 28362839, 2017). "Additionally, a recent paper demonstrated that cyclin D1b cooperates with AR signaling to promote tumor cell growth and metastatic behavior of PC cells, partially by inducing expression of the pro-oncogenic transcription factor SNAI2 (Slug)." (PMID 27741508, 2017). "In preclinical trials, darolutamide demonstrated higher binding affinity compared with other AR antagonists (such as bicalutamide and enzalutamide), an antiproliferative effect and tumor growth inhibition in AR-overexpressing cells, and activity against AR mutants linked to drug resistance." (PMID 28801852, 2017). "Given the potential prognostic importance of stromal AR expression, studies need to extend beyond speculative hypotheses to address in real time how AR levels fluctuate within a tumour sample." (PMID 28117763, 2017). "Both mutant AR and wildtype AR are expressed in this sample, but whether they were coexpressed in the same tumor cell is unknown." (PMID 28036278, 2017). "Thus, AR expression appears to be down-regulated or lost during steps of tumorigenesis and tumor progression in spite of the promoting effects of AR signals." (PMID 28241422, 2017). "Recent evidences demonstrate that tubulin-targeting drugs (docetaxel) cause cytoplasmic AR sequestration ex vivo and in circulating tumor cells, significant down-regulation of AR and PSA expression, and nuclear accumulation of the fork head transcription factor family member FOXO1." (PMID 27242530, 2016). "Unlike the traditional ones, sipuleucel-T and AR-directed therapies target tumor cells, thus causing little toxic effects on normal cells due to high selectivity." (PMID 28058266, 2016). "Since this mutant shows little response to AR antagonists, the broad activation by non-androgen steroids is probably responsible for the tumor growth observed in prostate models bearing this mutation." (PMID 26760770, 2016). "This suggests that elevated MYC expression in the NHPrE1/AR tissue recombinants may result from signals from other cellular components, such as immune cells, of the tumor microenvironment." (PMID 27611945, 2016). "Limited functional studies with renal cell lines suggested tumor-promoting activity of AR." (PMID 26814892, 2016). "Similar results were also obtained in mice with orthotopically xenografted AR knock-down OS-RC-2 cells; these mice exhibited smaller tumor sizes and masses than the siRNA scramble control mice, suggesting that AR signaling may promote RCC progression." (PMID 27848972, 2016). "Our data raise the possibility that AR-V7 mRNA, which is nearly universally expressed at <10% of the level of full-length AR, may be below the threshold of detection in circulating tumour cells unless AR gene copy number is increased." (PMID 27897170, 2016). "We speculate that at the molecular level, ID4 may integrate multiple regulatory pathways for example epigenetic re-programming, integration of multiple AR co-regulators or signaling pathways that may ultimately result in tumor suppressor activity of ID4." (PMID 27487149, 2016). "In addition, it was found that a triple negative tumor status was inversely related to the expression of the AR (p value <0.001)." (PMID 29083379, 2016). "This could be explained by a biphasic effects of AR activation observed in vitro in tumor cell lines." (PMID 26964090, 2016).
tumor (continued). "In our staining, however, the degree of AR expression did not appear to have an influence on likelihood of chemoresistance, implying that the presence of a functional AR in tumor cells is critical and may suffice for inducing drug resistance." (PMID 27322140, 2016). "GSK3beta has potent tumor suppressor qualities and decreased function may elicit increased activity of androgen receptor signaling." (PMID 27014907, 2016). "These diverse resistance mechanisms highlight the reliance of PCa on the maintenance of AR signaling, which controls a number of cellular pathways including metabolic fuelling of tumor growth, progression through cell cycle checkpoints, promotion of metastatic phenotypes, and DNA damage repair." (PMID 26657335, 2016). "Thus, our results further confirm that suppression of ligand-dependent AR function is a key determinant of the anti-tumor activity of JQ-1 in CRPC models." (PMID 27276681, 2016). "The tumor suppressive role of AR suggests that therapies that promote retention of AR signaling may be beneficial to ccRCC patients." (PMID 26814892, 2016). "At this stage, AR might promote PC metastasis by changing the tumor microenvironment composition or inducing the release of stromal growth factors." (PMID 26506594, 2016). "A target common to both enzalutamide and AA is the AR-signaling pathway, however these differ in their mechanisms of activity, with enzalutamide inhibiting AR directly and AA inhibiting extra-gonadal and intra-tumor androgen synthesis." (PMID 27756383, 2016). "Our findings support a tumor suppressor role for AR in both genders that might be exploited to decrease the incidence or progression of ccRCC." (PMID 26814892, 2016). "However, this reversal was observed at the late stage of tumor growth whereas at the earlier one any AR stimulation led to a significant decrease in tumor growth." (PMID 26964090, 2016). "We hypothesized that AR mRNA splicing alterations specific to this AR-GSR may be detectable using our strategy of mapping bulk tumour RNA-seq reads to a rearranged genome assembly." (PMID 27897170, 2016). "Also 44% of patients defined to have lost expression of AR in the primary tumor expressed AR in at least one metastatic lesion." (PMID 27384477, 2016). "Based on these findings, we reflected on the possible mechanism by which three discrete AR-GSRs that appeared to share overlap with one another could co-exist in tumours harbouring a single AR gene copy." (PMID 27897170, 2016). "KLK3 expression is primarily regulated by the androgen receptor, and it is a commonly used readout of the level of receptor activation both clinically and experimentally, and the most facile explanation is therefore that androgen receptor signalling is downregulated in more aggressive tumours." (PMID 27120785, 2016). "Of the 12 CRPC tumours that were positive for an AR-GSR event, 7 harboured multiple AR-GSRs." (PMID 27897170, 2016). "We here report the expression of AR, but not ERα or ERβ, in BC is associated with tumor recurrence in patients treated with ADT." (PMID 26885620, 2016). "This pattern of decreased AR in TRAMP mice may represent a transformation of the tumor to androgen independent disease." (PMID 27634876, 2016). "Interestingly, the study found an inverse correlation between the AR expression and tumor size, lymph node status, and histological grade." (PMID 27918430, 2016). "Furthermore, certain functional studies with renal cell lines suggested a tumor promoting role for AR." (PMID 26814892, 2016). "Mechanistically, ID4 may assimilate multiple regulatory pathways for example epigenetic re-programming, integration of multiple AR co-regulators or signaling pathways resulting in tumor suppressor activity of ID4." (PMID 27487149, 2016).
tumor (continued). "Despite this heterogeneity, one common outcome in tumours with high sub-clonal enrichment of AR-GSRs is outlier expression of diverse AR variant species lacking the ligand-binding domain and possessing ligand-independent transcriptional activity." (PMID 27897170, 2016). "AR-V7 has been linked to primary resistance to either abiraterone or enzalutamide, and monitoring AR-V7 status in circulating tumor cells (CTCs) over the course of treatment may predict sensitivity or resistance to AR-targeted agents." (PMID 27223078, 2016). "A modest but consistent decrease in the androgen receptor level has been shown when miR-9 was overexpressed in vitro, which could allow for an eventual switch from the early androgen-dependent tumour to a hormone-refractory state." (PMID 27447934, 2016). "This is perhaps due to a hypothesized dual role of miR-375 as either an onco-miR or a tumour suppressor miRNA, depending on the cellular context, in androgen receptor regulation or the tumour model." (PMID 27011184, 2016). "Inhibition of CHKA repressed the AR transcriptional program including pathways enriched for regulation of protein folding, decreased AR protein levels, and inhibited the growth of PCa cell lines, human PCa explants, and tumor xenografts." (PMID 26657335, 2016). "Well-differentiated, low-grade tumors contain glandular structures containing tumor cells that express known PCa markers such as androgen receptor (AR) and PSA, while poorly differentiated PCa tumors are lacking in glandular structures and differentiated cells." (PMID 27438858, 2016). "However, they will also offer new opportunities to elucidate ligand-dependent AR-interactome networks in a tumor-specific background." (PMID 27365400, 2016). "Castration resistant prostate cancer (CRPC) is characterized by increased activation and/or overexpression of androgen receptor (AR) resulting in the transcription of downstream target genes and tumor progression despite castrate levels of androgen in the patient." (PMID 27049719, 2016). "In addition, expression microarray analysis using xenograft tumor samples of isogenic androgen-sensitive and recurrent pairs showed that increased AR was the only gene expression alteration that was consistent over all 7 different CR-PCa xenograft models." (PMID 27487144, 2016). "Considering the variable hormone conditions and AR regulations in particular tissues, the strategy to decrease the androgen in tumor microenvironment or to inhibit its binding to AR may be promising ways in treatment of such male bias cancers." (PMID 27167111, 2016). "The underlying ID4 dependent molecular mechanisms could therefore be exploited to develop therapeutic strategies to re-activate AR as a tumor suppressor." (PMID 27487149, 2016). "In contrast, those with AR-positive or p-NF-κB-positive tumor may be resistant to CDDP therapy and are anticipated to benefit from combined anti-AR therapy." (PMID 27322140, 2016). "The prevalence of selected AR mutations was assessed in CRPC patients using the newly described BEAMing (Beads, Emulsions, Amplification, and Magnetics) technology to analyze circulating tumor DNA (ctDNA), and found to be at least 12%." (PMID 26760770, 2016). "Furthermore, Cox regression model confirmed that only AR (P=0.007), ERα/ERβ (P=0.032), tumour grade (P=0.047) and myometrial invasion (P=0.008) were independent prognostic indicators." (PMID 26930451, 2016). "ID4 may regulate a specific or combination of these pathways that may ultimately decide whether AR acts as a tumor suppressor or an oncogene." (PMID 27487149, 2016). "Collectively, our results suggested that ID4NC may redirect AR activity from being a tumor promoter to that of a tumor suppressor." (PMID 27487149, 2016).
tumor (continued). "Analysis of AR DNA-seq data demonstrated that 12/30 tumours (6/15 patients) in this metastatic CRPC cohort displayed AR gene amplification, which was defined as normalized coverage of the AR gene >1 when compared with normalized coverage at a set of control genomic regions." (PMID 27897170, 2016). "Therefore, AR-miR-204-XRN1 axis is probably one of the key mechanisms for dual regulatory function of AR in different stages of tumor progression of PCa." (PMID 27438705, 2016). "GR and AR staining was performed on both the primary tumor and the recurrence (when available)." (PMID 27386391, 2016). "The data we presented suggest that AR is a tumor suppressor, and that devising ways to maintain or restore AR expression in RCC could have therapeutic benefit." (PMID 26814892, 2016). "In immunohistochemical findings, the tumor cells were positive for pan-cytokeratin, cytokeratin 7, epithelial membrane antigen, gross cystic disease fluid protein-15, and androgen receptor (AR), confirming the apocrine origin of the tumor." (PMID 27668109, 2016). "Interestingly, tumours C-6A and C-6B also displayed the lowest levels of full-length AR mRNA expression across the cohort of CRPC metastases." (PMID 27897170, 2016). "If AR is in fact a tumor suppressor, then treatment of patients bearing AR-expressing RCC with AR antagonists could be deleterious and promote, rather than prevent, progression." (PMID 26814892, 2016). "It is also possible that in CD73-depleted mice model, the activation of a single AR could be insufficient to stimulate cell proliferation at the early stage of tumor growth, with much less abundant tumor-derived growth factors." (PMID 26964090, 2016). "Notably, the expression of both KLF4 and AR was low in tumor tissue samples with low miR-1 expression." (PMID 27991915, 2016). "Results demonstrated that inhibition of both miR-101 and miR-27a not only markedly increased tumour growth but also promoted lymphatic metastasis as indicated by androgen receptor (AR) or GFP staining, confirming that metastatic loci in the mouse lymph node came from LNCaP cells." (PMID 27108958, 2016). "AR expression was correlated with pathological tumor features of the primary tumor." (PMID 26552477, 2015). "Current evidence indicates that reactivation of androgen receptor (AR) in tumor cells may play a critical role in the development of castration resistant prostate cancer (CRPC)." (PMID 25950519, 2015). "We speculate that in normal prostate cell, the AR and miR-124 expressions are at a balance as proposed for that occurring between proto-oncogenes and tumor suppressors." (PMID 25860954, 2015). "Moreover, the docetaxel has been shown to lead to CRPC tumor regression via impairing AR nuclear translocation and activity by a microtubule-associated mechanism." (PMID 26512780, 2015). "Very little is known regarding discrepancies of AR status during tumor progression." (PMID 26552477, 2015). "This study supports the hypothesis that expression of HOXC11 and the subsequent secretion of PSAP can expedite endocrine resistance to aromatase inhibitor therapy via tumour promotional activation of the AR." (PMID 26341737, 2015). "Intratumoral de novo biosynthesis of androgen in CRPC tumor cells may also provide for ligand-dependent activation of AR." (PMID 25950519, 2015). "Moreover, the combined treatment significantly inhibited tumor-cell proliferation, androgen-receptor expression, and PIK3/Akt signaling, and induced apoptosis in vivo." (PMID 25918934, 2015). "AR positivity was defined as any nuclear staining in tumor cells ≥1 %." (PMID 26552477, 2015).